BCL11A (BCL11 transcription factor A)
Diseases named in the same sentence as BCL11A in open-access papers (continued):
Sharing a sentence is not in itself a finding about the gene and the disease.
tumor (continued). "B‐cell chronic lymphocytic leukemia/lymphoma 11 A (BCL11A), as a transcription factor, is oncogenic in several neoplasms." (PMID 32625084, 2020). "LSCC cells overexpressing BCL11A were injected into immunocompromised recipient mice to induce tumor development." (PMID 32266150, 2020). "miR-137 acts as a tumor suppressor by suppressing B-cell lymphoma/leukemia 11A (BCL11A) expression, leading to the inhibition of CSCs’ self-renewal and proliferation ability, and shrinkage of the tumor mass." (PMID 31861404, 2019). "We then injected control or BCL11A-KD cells into immune compromised mice to test for their tumour formation capacity and found a significant reduction in tumour burden from BCL11A-KD cells compared to control cells." (PMID 30127402, 2018). "We show that BCL11A upregulation leads to early stages of tumour development in the mouse and is critical for tumour maintenance even in the presence of SOX2." (PMID 30127402, 2018). "qRT–PCR analysis of this tumour revealed expression of Bcl11a probably owing to incomplete Cre-loxP recombination (sample T1)." (PMID 25574598, 2015). "Exogenous BCL11A overexpression promotes tumour formation, whereas its knockdown in TNBC cell lines suppresses their tumourigenic potential in xenograft models." (PMID 25574598, 2015). "Prior studies had revealed crucial roles for Bcl11a in regulating blood development and diseases, and for Runx1t1 in midgut development and neoplasias of blood, lung and breast." (PMID 25330008, 2014). "Similarly, Bcl11a and Chd8 protein levels were also elevated in tumours derived from the mouse TNBC model (Brca1f/fp53+/-Blg-Cre)." (PMID 40328966, 2025). "Along with other key epigenomic drivers of nephrogenesis, including other SWI/SNF complex constituents or downstream PRC2 complex components, BCL11A appears to play a role in the differentiation program of nephron progenitor cells, further supporting its potential as a tumor suppressor candidate." (PMID 40772033, 2025). "Despite its key role in driving tumour development no significant mutations have been reported in BCL11A, suggesting a strong selection pressure to keep it intact." (PMID 40328966, 2025). "The diverse modes of regulation and the occurrence of the post-transcriptional modifications of BCL11A pre-mRNA suggest a very complex way of controlling BCL11A expression levels, which is most likely dependent on the type of cancer and possibly on the histological type of the same tumor." (PMID 37372998, 2023). "Our findings suggest that the nuclear expression of BCL11A in NSCLC cells may affect the proliferation of tumor cells and change their phenotype, thus promoting tumor progression." (PMID 37372998, 2023). "Moreover, the results obtained from the entire NSCLC cohort showed a weak correlation of nuclear BCL11A expression with the primary tumor size measured in centimeters (r = 0.127, * p = 0.0455)." (PMID 37372998, 2023). "In addition, when we analyzed AC cases, we noted higher nuclear expression of BCL11A in pT3 and pT4 tumors compared to pT1 and pT2 (p = 0.0134) and in cases with tumor stage III and IV compared to I and II (p = 0.0341)." (PMID 37372998, 2023). "Moreover, in the whole cohort and the AC subtype, we observed a decrease in the cytoplasmic expression of BCL11A with increasing tumor size and the percentage of necrosis." (PMID 37372998, 2023). "In addition, we observed that ZNF488 and BCL11A were positively related to the advanced tumor stage and stemness." (PMID 35571561, 2022). "The staining of BCL11A in NB tissues was observed in the cytoplasm and nucleus of tumor cells." (PMID 35909289, 2022). "Predictions based on the LINC00899/PSMG3-AS1/PAXIP1-AS1- hsa-miR-210-3p-CPEB2 and SNHG16- hsa-miR-190b-BCL11A ceRNA regulation networks indicated that the two genes might act as tumor suppressor and oncogene, respectively." (PMID 33344235, 2020).
tumor (continued). "To investigate if BCL11A is required for SOX2-mediated oncogenesis we introduced a doxycycline inducible BCL11A overexpression vector into SOX2-KD cell lines and found that BCL11A overexpression partially rescues the colony and tumour formation abilities of SOX2-KD cells." (PMID 30127402, 2018). "The BCL11A spans 102 kb on 2p16 and is involved in several tumours." (PMID 28225775, 2017). "Furthermore, high BCL11A expression in BLBC cases was further validated by immunohistochemistry (IHC) on a subset of the METABRIC tumours (all subtypes, n=368." (PMID 25574598, 2015). "Also, qRT–PCR and IHC results revealed that tumours upregulated Bcl11a expression in response to DMBA-induced carcinogenesis." (PMID 25574598, 2015). "To address this, we first tested whether BCL11A overexpression could promote the colony formation or tumour development in mammary epithelial cells." (PMID 25574598, 2015). "In addition, we also found that high BCL11A expression in METABRIC samples correlated with the recently described IC10 cluster of tumours, thus further supporting the concordance between the BLBC and IC10 classifications." (PMID 25574598, 2015). "Similarly, three out of four mice injected with HMLE-11A cells developed tumours within 8 weeks of injection suggesting that elevated levels of BCL11A promote tumour development." (PMID 25574598, 2015). "In contrast, the BCL11A knockdown cells produced tumours of significantly reduced sizes." (PMID 25574598, 2015). "Similarly, in the UNC040182B tumor sample, a micro-deletion in the BCL11A gene results in mRNA-seq reads that align outside of the exon containing multiple sequence errors, a finding likewise not observed in the unaffected SUM102 cell line data." (PMID 23284754, 2012). "So BCL11A-XL might play an essential role in tumor development." (PMID 36030436, 2023). "Notably, higher expression levels of genes exclusively expressed in the C14 and C38 B cell types (such as BCL11A and DNASE1L3) were positively associated with favorable prognoses, indicating the tumor-suppressive functions of C14 and C38 cells in the PDAC microenvironment." (PMID 38149248, 2023). "Also BCL11A-XL expressed in a range of tumor-derived cell lines." (PMID 36030436, 2023). "However, once the tumor is established, BCL11A might inhibit cancer metastasis and improve the sensitivity of chemo- or radiotherapy, thereby contributing to better survival." (PMID 23758992, 2013). "We show that CHD8 also plays a key role in TNBC pathogenesis, with detailed multi-omics analysis revealing that BCL11A and CHD8 co-regulate several targets and synergise to drive tumour development and progression." (PMID 40328966, 2025). "Other predicted targets for hsa-miR-29c are BCL11A and COL22A1, involved in tumour formation, regulator of structural molecular activity and extracellular region." (PMID 32182819, 2020). "On the other hand, 3 genes (ANKRD11, BCL11A, and FOXN3) out of the top 5 mythelated genes in cluster 6 are well-known in their anti-tumor action." (PMID 32272578, 2020). "High levels of BCL11A promotes TNBC development while knockdown of BCL11A sharply decreases the tumorigenicity of TNBC cells and reduces the tumor size in mice model." (PMID 31654056, 2019). "Similar to BCL11A we found that SOX2-KD cells had a significantly reduced colony and tumour formation abilities." (PMID 30127402, 2018). "Different plasma BCL11A levels were detected in patients at different stages of LSCC; the plasma BCL11A levels were seen to increase with the tumour staging." (PMID 28225775, 2017). "Experimentally, we have shown that disrupting BCL11A expression in TNBC cell lines and in the mouse significantly reduced tumour development and maintenance." (PMID 25574598, 2015). "The tumor cells of BPDCN and PPDM share the common characteristic phenotype of pDCs: lin−, CD4+, CD68+, CLA+, CD123+, BDCA2+, Bcl11A+ and CD2AP+." (PMID 25779340, 2015).
tumor (continued). "By investigating cancer genomics data from ~3,000 patients (METABRIC and TCGA), BCL11A was significantly expressed at higher levels in TNBC and particularly in BLBC/IC10 tumours both at RNA and protein levels." (PMID 25574598, 2015). "Therefore, one wonders whether BCL11A inhibits cancer metastasis and acts as a tumor suppressor." (PMID 23758992, 2013). "Furthermore, miR‐137 disrupts the interaction between BCL11A and DNMT1, reducing cancer stemness and inhibiting tumour progression in TNBC." (PMID 40387409, 2025). "Particularly, ek2 is distinguished in transcription regulation and biological function, because it enriched FKBP10, a promoter for tumor proliferation and invasion through the crosstalk to PIK3 pathway, BCL11A and MSC, the tumor stemness-related transcription factors." (PMID 38331768, 2024). "The negative correlations between the expression level of BCL11A, the grade of histological malignancy (G), and the size of the tumor allow us to assume that BCL11A plays a role in the initiation of tumor transformation." (PMID 37185699, 2023). "Additionally, silencing of BCL11A reduced the levels of SCC markers (KRT5 and TP63) and inhibited tumor growth." (PMID 37372998, 2023). "Nuclear expression of BCL11A in NSCLC cells may affect tumor cell proliferation and change their phenotype, thus promoting tumor progression." (PMID 37372998, 2023). "Similarly, B-cell lymphoma/leukemia 11A (BCL11A) contributes to formation and invasion of tumor cells, stem cell self-renewal and activation of signalling by Wnt/β-Catenin and the EMT pathway." (PMID 35205716, 2022). "All in all, our findings indicate that circKIF4A may influence NKTL tumor growth through modulating PDK1 and BCL11A expression by functioning as a ceRNA for miR-1231." (PMID 36230873, 2022). "In conclusion, BCL11A was overexpressed in NKTL, while its upregulation promoted tumor development." (PMID 32625084, 2020). "In their study, BCL11A was specifically overexpressed in tumor tissues rather than paracancer tissues." (PMID 32266150, 2020). "Experimentally we demonstrate that non-physiological levels of BCL11A in vitro and in vivo promote squamous-like phenotypes, while its knockdown abolishes xenograft tumour formation." (PMID 30127402, 2018). "We found GMPs, MDPs, and CDPs from tumor-bearing mice failed to upregulate proteins indicative of the cDC program (e.g., Irf8, Zbtb46, Cd209a, Spib, Batf3, and Bcl11a)." (PMID 29593283, 2018). "Both SOX11 and TPX2 showed a trend of increased expression levels with increasing tumor grade, whereas BCL11A did not." (PMID 23506684, 2013). "NCBI Entrez gene database reported that: CHEK2 is a cell cycle checkpoint regulator and putative tumor suppressor, and associated with GBM; GSTM5 was reported to be involved in cancer, BCL11A is a proto-oncogene, and FN1 is involved in tumor metastasis and angiogenesis." (PMID 21114830, 2010). "Apart from a few zinc-finger proteins, such as WT1, BCL11A, Evi9, EWS, TLS, GLI, and CTCF, the function of the majority of zinc-finger proteins in tumour occurrence and development is unknown." (PMID 15354214, 2004). "Additionally, upregulation of miR‐137 or silencing of BCL11A resulted in a decrease in the number of tumorspheres and the proportion of CSCs in both MDA‐MB‐231 and SUM149 cell lines, while also exerting an inhibitory effect on tumour growth in vivo." (PMID 40387409, 2025). "In addition, we found a negative correlation of the cytoplasmic expression of BCL11A with the size of the primary tumor measured in centimeters (r = −0.228, p = 0.0001) and the percentage of necrosis (r = −0.299, p < 0.0001)." (PMID 37372998, 2023). "Furthermore, BCL11A is known as a non-autonomous T cell tumor suppressor." (PMID 30965648, 2019). "Moreover, the expression of both BCL11A and SOX2 was significantly higher in LUSC but not in LUAD tumour samples compared to patient matched normal samples supporting a driver role for these transcription factors in LUSC pathology." (PMID 30127402, 2018).
tumor (continued). "However, the TCGA data does not indicate a strong correlation between BCL11A and SIRT1 or MDM2 expression at least in the tumour context." (PMID 25574598, 2015).
cancer (44 papers, 2010 to 2025). A tumor composed of atypical neoplastic, often pleomorphic cells that invade other tissues. "Previous studies have shown that BCL11A is also highly expressed in some hematological malignancies and malignant solid tumors, and is associated with poor clinical prognosis." (PMID 31654056, 2019). "BCL11A (B-cell lymphoma/leukemia 11A) gene is a cancer gene that encodes the C2H2 zinc finger transcription factor and a component of the BRAF complex, which has been shown to be associated with the regulation of cell proliferation, apoptosis, and transformation." (PMID 36230873, 2022). "The BCL11A gene, which spans over 102 kb on chromosome 2p16, is associated with various cancers." (PMID 32266150, 2020). "To avoid false BCL11A mRNA expression results due to the presence of lymphocytes among the cancer cells, we had to significantly reduce the number of samples for molecular studies." (PMID 37372998, 2023). "To date, only a few papers have been published on the significance of BCL11A in this type of cancer." (PMID 37185699, 2023). "A link between high BCL11A expression and a worse prognosis has been demonstrated in patients with various cancers." (PMID 37185699, 2023). "Recently, BCL11A has attracted widespread attention as a prognostic marker and potential therapeutic target in malignant neoplasms." (PMID 35909289, 2022). "Compared with other cancers, higher expression levels of BCL11A were observed in NB cell lines and primary tumors." (PMID 35909289, 2022). "In TP astrocyte, OPC and NFO, the notable TF, BCL11A, is involved in microRNAs in cancer, whereas the TF SIX5 is seen to regulate highest number of processes such as regulation of GTPase activity, cell growth, complement activation, lectin pathway etc." (PMID 34976314, 2022). "Several studies showed that the upregulation of BCL11A contributes to cancer development through various pathways in certain solid tumors." (PMID 32625084, 2020). "Since lncRNAs are associated with cancer growth and progression by cancer pathways, activity of PI3K/AKT and MAPK signaling pathways in TAM resistance is mediated by uc.57/BCL11A." (PMID 29179465, 2017). "In this study we interrogated cancer genomics data focusing on a subset of important hematopoiesis factors and identified BCL11A as a novel TNBC oncogene." (PMID 25574598, 2015). "Notably, the inhibition of either DNMT1 or BCL11A results in a compromised capacity for cancer stemness and tumorigenesis in TNBC, which is achieved through the suppression of ISL1 expression both in vivo and in vitro." (PMID 40387409, 2025). "Malignancies were queried because somatic variants in BCL11A are reported in sporadic malignant tumors, however no individuals had been diagnosed with solid or hematologic malignancies." (PMID 39448799, 2025). "In conclusion, determining the expression level of BCL11A, its localization in cancer cells and relationship with clinicopathological factors may bring us closer to the understanding of the role of this protein in carcinogenesis." (PMID 37372998, 2023). "Reactions carried out on cancer cells showed significantly higher BCL11A expression in the MCF-7 line (761.14 ± 31.82) compared to the SK-BR-3 (630.58 ± 34.75, ** p < 0.01), MDA-MB-468 (568.37 ± 21.14, *** p < 0.0001), and MDA-MB-231 (460.75 ± 56.09, *** p < 0.0001) lines." (PMID 37185699, 2023). "However, we still do not know the exact mechanisms of BCL11A, its interactions with other proteins, or the signaling pathways in which BCL11A is involved and through which it affects normal and cancer cells." (PMID 37372998, 2023). "Previous studies showed that high expression levels of PDGFC, SOX9, BCL11A, and DIO2 were associated with poor response to chemotherapy in cancer cells and short survival time of various patients, which could be regarded as negative prognostic factors." (PMID 36092919, 2022). "This indicates that ZNF488 or BCL11A increases the stemness of cancer cells." (PMID 35571561, 2022).
cancer (continued). "In cancer, the role of BCL11A protein appears to be context-dependent." (PMID 31561579, 2019). "BCL11A also participates in human diseases and functions as an oncogene in some malignant tumors." (PMID 31654056, 2019). "Reporting the role of BCL11A (B-cell lymphoma/leukemia 11A) in malignant solid tumors is rare, but overexpression of BCL11A has been detected in some malignant solid tumors, suggesting that this gene may be a valuable diagnostic and prognostic tool for these tumors." (PMID 40051609, 2025). "Therefore, it is likely that BCL11A is downregulated during the process of cancer occurrence." (PMID 40051609, 2025). "Two mechanisms may explain the abnormal activation of BCL11A in these malignant tumors." (PMID 31654056, 2019). "Silencing of BCL11A gene expression by miR-137 or disruption of BCL11A-DNMT1 (DNA methyltransferase 1) interaction reduced the number of cancer stem cells and inhibited cancer development." (PMID 37185699, 2023). "Given the importance of BCL11A in cancer, and this case report, it will be important to determine over time if other individuals with DLS/BCL11A-ID are diagnosed with WT or other cancer types, if screening is necessary, and what age range of screening would be most appropriate." (PMID 40772033, 2025). "After the study of induced pluripotent stem cells (iPS), which enabled dedifferentiation by regulating four genes, an extended study revealed that two regulators, BCL11A and HDAC1/2, have been identified in the gene regulatory network for reprogramming cancer cells." (PMID 38536842, 2024). "Nevertheless, our data showed that inhibition of BAF155 methylation resulted in dissociation of HDAC1, and recruitment of BCL11A and PBAF to activated ISGs, implying that BAF155 methylation represents a therapeutic vulnerability for targeting the SWI/SNF complex in cancer treatment." (PMID 34865122, 2021). "In these specific intergroup DE genes, BCL11A, VPREB3, CD79B, CHRNA7, and SWAP70 that all involved in B cell proliferation and activation, would likely impact B cell function in MDV pathogenesis and malignant tumor formation." (PMID 30922224, 2019). "BCL11A was highly and specifically expressed in cancer tissues rather than adjacent non-cancerous tissues." (PMID 23758992, 2013). "Based on our gene expression profiling data, we found that BCL11A was differentially expressed between cancer and adjacent non-cancerous tissues, with 3.06-fold upregulation in cancer tissues (t = 9.81, P < 0.001)." (PMID 23758992, 2013). "Interestingly, the three other proteins RXRA, BCL11A and ELK1 are also related to cancer." (PMID 27203237, 2016). "Furthermore, we found that in a subgroup of patients with early stage cancer (IA–IIB), and in particular early SCC, BCL11A was not only a significant prognostic factor for DFS (HR 0.18, 95% CI 0.05–0.66, P = 0.01), but also for OS (HR 0.17, 95% CI 0.06–0.50, P = 0.001)." (PMID 23758992, 2013). "Whether comparing between all cancer and adjacent tissues or just between paired cancerous and non-cancerous tissues, BCL11A mRNA was upregulated in cancer tissues." (PMID 23758992, 2013). "When compared to patients with advanced stage NSCLC and lymph node involvement, BCL11A expression was much higher in patients with early stage cancer and no lymph node involvement, which suggests that activation of the BCL11A proto-oncogene might be an early stage event in NSCLC." (PMID 23758992, 2013).